RNU6-565P (RNA, U6 small nuclear 565, pseudogene)
Gene: Small nuclear RNA gene on chromosome 7 (37,351,143 to 37,351,242, forward strand). Ensembl gene ENSG00000222869.
Homologues: Orthologues: chimpanzee U6 (99% identical). Paralogues in human: RNU6-1251P (76% identical), RNU6-242P (76% identical), RNU6-41P (76% identical), RNU6-429P (76% identical), RNU6-476P (76% identical), RNU6-590P (76% identical), RNU6-657P (76% identical), RNU6-692P (76% identical), RNU6-1019P (75% identical), RNU6-1029P (75% identical), RNU6-1113P (75% identical), RNU6-1131P (75% identical), and 1286 more.